SPATA31A1 (SPATA31 subfamily A member 1)
Description:
May play a role in spermatogenesis.
Synonyms: C9orf36; FAM75A1; FAM75A2; SPATA31A2; DKFZP434B204; C9orf36A
Tractability: Antibody: UniProt predicts a signal peptide or a membrane-spanning region.
Gene: Protein-coding gene on chromosome 9 (39,355,669 to 39,361,962, forward strand). Ensembl gene ENSG00000204849.
Subcellular location: Membrane
Subcellular location (Human Protein Atlas): Acrosome; Equatorial segment
Gene Ontology:
Cellular component: membrane
Genetic constraint (gnomAD): Loss-of-function variants: 0 observed, 4.5 expected, observed/expected ratio (o/e) 0, 90% interval 0 to 0.67. That is too few expected variants to judge how well the gene tolerates losing a copy. Missense variants: 553 observed, 992.41 expected, observed/expected ratio (o/e) 0.56, 90% interval 0.52 to 0.6. Synonymous variants: 182 observed, 366.74 expected, observed/expected ratio (o/e) 0.5, 90% interval 0.44 to 0.56.
Homologues: Orthologues: rat Spata31 (27% identical), mouse Spata31 (27% identical). Paralogues in human: SPATA31A7 (98% identical), SPATA31A3 (98% identical), SPATA31A5 (98% identical), SPATA31A6 (98% identical), SPATA31C1 (76% identical), SPATA31C2 (73% identical), SPATA31E1 (34% identical), SPATA31D1 (27% identical), SPATA31D3 (18% identical), SPATA31D4 (18% identical), SPATA31F1 (17% identical), SPATA31F3 (2% identical).
Diseases named in the same sentence as SPATA31A1 in open-access papers:
SPATA31A1 is named in the same sentence as 1 disease in open-access papers, as found by Europe PMC text mining. Sharing a sentence is not in itself a finding about the gene and the disease. The quoted sentences say what the papers report.
anaphylaxis (1 paper, 2025). An acute hypersensitivity reaction that occurs from exposure to an allergen. "However, based on their known biological roles—POTEF in retinal homeostasis, MUC4 in mucin production, and SPATA31A1 in cell differentiation and spermatogenesis —it is unlikely that these genes are directly involved in the pathogenesis of cefaclor‐induced anaphylaxis." (PMID 40974473, 2025).